DRD2 (dopamine receptor D2)
Diseases named in the same sentence as DRD2 in open-access papers (continued):
Sharing a sentence is not in itself a finding about the gene and the disease.
breast cancer (29 papers, 2018 to 2024). A primary or metastatic malignant neoplasm involving the breast. "Our study showed that anemic breast cancer patients with a high number of chemotherapy cycles and those carrying at least one C allele for DRD2 and CLOCK SNPs are at greater risk of exhibiting fatigue." (PMID 34979978, 2022). "Increased expression levels of DRD2 mRNA have been reported in breast cancer patients, so it is expected that the risk of breast cancer with antipsychotics and the actions and mechanisms mediated by dopamine receptors will be further elucidated." (PMID 33789764, 2021). "And several specific DRD2 agonists like bromocriptine have already used clinically in nervous system disorder 32, 33, and molecular mechanism underlying DRD2 anti-tumor effects might facilitate to breast cancer treatment by using selective DRD2 agonists." (PMID 33859743, 2021). "In breast cancer, DRD2 regulates the microenvironment because it promotes the M1-polarization of macrophages and triggers thermal apoptosis performed by GSDME." (PMID 36980514, 2023). "In the only studies in cancer, the expression of both DRD2 and DRD3 was found to be increased in breast cancer patients, and DRD2 and DRD3 were found to have the same expression levels in the cholangiocarcinoma cell lines Mz-chA-1 and SG231." (PMID 36456906, 2022). "DRD2 serves as tumor suppressor and triggers pyroptosis in breast cancer, while its overexpression promotes CRC progression." (PMID 34438367, 2021). "In this study, DRD2 was confirmed to suppress tumorigenesis if breast cancer through interacting with DDX5 and eEF1A2." (PMID 33859743, 2021). "In breast cancer, DRD2 was found to exert anti-tumor effects when it locates in cellular membrane and in cell." (PMID 33859743, 2021). "Overexpression of DRD2 has been found in gastric cancer, neuroendocrine tumors, glioblastoma, breast cancer, cervical cancer, and colorectal cancer, and have variable association with survival with each histologic subtype." (PMID 33194693, 2020). "Research demonstrated that dopamine inhibits angiogenesis and thereby tumour growth in animal models of colon cancer, ovarian cancer, and breast cancer via activation of dopamine receptor D2 (DRD2)." (PMID 31478179, 2020). "TFP also showed potentials to treat bone metastasis of breast cancer by antagonizing dopamine receptor D2 (DRD2) and suppressing bone resorption." (PMID 31572198, 2019). "Together, these data indicate that DRD2 mRNA and protein can be detected in many breast cancer cell lines." (PMID 31822725, 2019). "We then compared the abundance of these two DRD2 bands across the panel of 11 breast cancer cell lines." (PMID 31822725, 2019). "DRD2 transcripts were undetectable in the many of the breast cancer cell lines we tested, suggesting that DRD2 is not likely to be the ONC201 target responsible for the effects we have observed." (PMID 29719618, 2018). "Furthermore, a study reported by Yiqing Tan novelly manifested the role of DRD2 in suppressing breast cancer tumorigenesis and further revealed that DRD2 educated M1 macrophages and restricted the NF-κB pathway, triggering pyroptosis in breast cancer." (PMID 36119049, 2022). "This indicates that dopamine is present in human breast tumors, and in the mouse C3-tag genetic breast tumor model, and suggests that DRD2 activation could potentially occur downstream of dopamine, supporting self-renewal of breast cancer cells." (PMID 31822725, 2019). "Although we have previously shown that 1–2 μM thioridazine requires DRD2 to inhibit self-renewal in basal-like breast cancer cell lines, thioridazine may block self-renewal through the inhibition of other receptors." (PMID 31822725, 2019). "Since DRD2 shoule be activated in order to support the self-renewal of breast cancer cells, and DRD2 activity is stimulated primarily by dopamine, we sought to determine whether dopamine itself could be detected in cell lines and human breast cancer tissue." (PMID 31822725, 2019).
breast cancer (continued). "We show that DRD2 mRNA and protein can be detected in all breast cancer cell lines tested, suggesting DRD2 expression alone cannot be used to predict whether the self-renewal of a cell line will be sensitive to thioridazine." (PMID 31822725, 2019). "To test whether this antibody detects DRD2-specific bands in breast cancer cell lines we knocked down DRD2 in a thioridazine-sensitive cell line (SUM229-EpCAM+) and a thioridazine insensitive cell line that expresses DRD2 mRNA (SUM159), and ran western blots using this anti-DRD2 antibody." (PMID 31822725, 2019). "The overexpression of DRD2 and DRD3, with concomitant silencing of DRD5 expression, confirms the presence of dopaminergic abnormalities in breast cancer patients." (PMID 38928253, 2024). "We analyzed a total of 6 genes: ESR1, DRD2, LINE1, MST1R, that we have previously demonstrated to be differentially methylated in prostate and breast cancers." (PMID 36067197, 2022). "A recent study reported that DRD2 can regulate the tumor microenvironment and facilitate M1 polarization of macrophages and activated GSDME-executed pyroptosis in breast cancer." (PMID 35712671, 2022). "DRD2 is an agonist of DRD5, and its high expression has been reported in many cancers, including breast cancer, ovarian cancer, and lung cancer." (PMID 34768458, 2021). "We then compared the responses to treatment with quinpirole, a dopamine receptor D2 (D2R)‐specific agonist, with those to treatment with aripiprazole in MCF‐7 cells to determine whether the underlying mechanism of aripiprazole‐induced apoptosis in breast cancer cells involved D2R signaling." (PMID 31301124, 2019). "Besides, in the context of cancer, a research on breast cancer 55 also indicated that, TAMs further promoted GSDME expression in dopamine receptor D2 (DRD2)-transfected BrCa cells during co-culture." (PMID 38817865, 2024). "Similarly, the dopaminergic system, highlighted in recent studies, indicates that dopamine receptors, particularly DRD2 and DRD3, are upregulated in breast cancer, potentially contributing to tumor growth and progression." (PMID 39123356, 2024). "We also show that all breast cancer cell lines tested express DRD2 mRNA and protein, regardless of thioridazine sensitivity." (PMID 31822725, 2019). "Furthermore, the integration of network pharmacology and molecular docking analyses revealed key targets associated with the anti-tumor effects of the pericarp, including PTGER3, DRD2, and ADORA2A, which present novel therapeutic targets for breast cancer treatment." (PMID 39682950, 2024). "On the contrary, DRD2, involved in restricting NF-κB signaling and EMT in breast cancer (BC), undergoes downregulation due to promoter hypermethylation." (PMID 38279330, 2024). "It is intriguing to speculate that the basal-like cell lines are releasing dopamine, leading to DRD2 activation through an autocrine mechanism, while the cell lines from other breast cancer subtypes are not." (PMID 31822725, 2019). "No direct evidence of ONC201 binding to DRD2/3 has been shown, gene suppression or deletion of DRD2/3 did not abrogate the ONC201’s cytotoxic effect, and DRD2 transcript is not detectable in many breast cancer cell lines that are sensitive to ONC201." (PMID 37046596, 2023). "In breast cancer cells, thioridazine has been found to inhibit self-renewal via DRD2-dependent STAT3 inhibition as well as induce a G1 cell cycle arrest independent of DRD2." (PMID 33922599, 2021).
glioma (25 papers, 2020 to 2026). A benign or malignant brain and spinal cord tumor that arises from glial cells (astrocytes, oligodendrocytes, ependymal cells). "Consistently, DRD2 knockdown also abolished the NE-induced protein upregulation of Wnt/β-catenin pathway in both glioma cells." (PMID 37415171, 2023). "Taken together, both the in vitro and in vivo results indicate that DRD2 indeed mediated the promoting effect of chronic stress on glioma progression." (PMID 37415171, 2023). "In this study, we found that chronic stress promotes glioma malignant progression and identified DRD2 as the novel regulator." (PMID 37415171, 2023). "Several drugs, including HDAC inhibitors and the selective dopamine receptor D2 antagonist ONC201, are being investigated in clinical trials for K27M-mutated pediatric glioma (NCT02717455, NCT03416530)." (PMID 37221626, 2023). "Analogously, a study carried out in an orthotopic rat model of glioma provided evidence indicating that DRD2 signalling induces a shift in the functional phenotype of macrophages from M2 to M1 and attenuates tumour growth." (PMID 36428964, 2022). "In this line, a combined application of temozolomide and DRD2 antagonists was shown to have synergistic effects in inhibiting the proliferation of glioma cells." (PMID 33806345, 2021). "In gliomas harboring the H3K27M mutation, dopamine receptor D2 is overexpressed and dopamine receptor D5 is suppressed, resulting in enhancement of sensitivity to a dopamine receptor D2 antagonist." (PMID 33673070, 2021). "Therefore, DRD2 knockdown or inhibition largely abolished the promoting effect of NE on glioma proliferation in vitro." (PMID 37415171, 2023). "Since the glioma in mouse brain showed that mRNA levels of PD-L1 were lower in the paliperidone treatment group, we further determined whether DRD2 expressed in mouse GBM changes the polarization of TAMs under interaction of GBM and macrophages." (PMID 34503167, 2021). "But DRD2 was also found to be essential in DA-reprogrammed M1 Mφ in glioma, which could be reversed by the DRD2 antagonist or deletion." (PMID 33859743, 2021). "Therefore, for glioma patients with high psychological depression, personalized and precise molecular targeted therapy targeting DRD2 and TMZ may be an effective treatment." (PMID 37415171, 2023). "Previous work has revealed that high expression of DRD2 mRNA and protein was observed in glioma tissues and DRD2 contributes to the spheroid formation behavior of U87 glioma cells, promotes glioma cell proliferation and maintains the self-renewal of glioma-initiation cells." (PMID 37415171, 2023). "PRRX1 could potentiate glioma-initiating cells via DRD2-mediated ERK and AKT activation." (PMID 33987093, 2021). "In these gliomas, the GPCR directly antagonized by ONC201, dopamine receptor D2 (DRD2), acts to promote tumor growth." (PMID 37601686, 2023). "In this study, we revealed that DRD2/ERK/β-catenin pathway and Dopamine/ERK/TH regulatory loop jointly mediate the promoting effect of chronic stress on glioma malignant progression." (PMID 37415171, 2023). "ONC201, a dopamine receptor D2 (DRD2) antagonist and caseinolytic protease P (ClpP) agonist, has induced durable tumor regressions in adults with recurrent H3 K27M-mutant glioma." (PMID 36382108, 2022). "This was the case for SEMA5A (FDR = 0.0855), DRD2 (FDR = 0.00623) and SOSTDC1 (FDR = 0.0234), which have all been found to act as tumor suppressors in pancreas cancer, glioma, non-small cell lung cancer and thyroid cancer." (PMID 34604945, 2021).
glioma (continued). "Dopamine and its receptor (DRD1–3) are also neurotransmitters that have been associated with increased endometrial cancer severity and reduced progression-free survival, with the DRD2 antagonist ONC201 shown to reduce tumour growth in vivo, including the highly aggressive H3K27M mutant gliomas." (PMID 37371546, 2023). "In addition, the follow-up results exhibited that glioma patients with higher DRD2 expression showed poorer prognosis than those with lower DRD2 expression, while this was not the case for β-catenin." (PMID 37415171, 2023).
bipolar disorder (24 papers, 2009 to 2025). A disorder of the brain that causes unusual shifts in mood, energy, activity levels and the ability to carry out day-to-day tasks. "Additionally, DRD2 is also associated with several neuropsychiatric disorders including ADHD, autism spectrum disorder (ASD), and bipolar disorder (BD)." (PMID 37957291, 2024).
glioblastoma (22 papers, 2014 to 2025). The most malignant astrocytic tumor (WHO grade IV). "Adenosine A2A receptor‐targeting minor molecule antagonist AZD4635 and ONC201, an imipramine that antagonizes the dopamine receptor D2 (DRD2) and has demonstrated efficacy in glioblastoma in phase II trials, are noteworthy examples." (PMID 40969301, 2025). "Dopamine exerts a proliferative effect on glioblastoma cells via the activation of the dopamine receptor D2 (DRD2)." (PMID 38567163, 2024). "In 2023, Wang and collaborators discovered that long-term stress boosts glioblastoma by increasing DA and DRD2 levels through the DRD2/ERK/β-catenin pathway and the DA/ERK/TH regulatory loop." (PMID 39335492, 2024). "Knockdown of nine PTGs significantly decreased cell viability, of which lower expression levels of DRD1, DRD2, HTR3A and TACR1 were also associated with better patient survival in The Cancer Genome Atlas (TCGA) glioblastoma cohort." (PMID 39304781, 2024). "Recent studies have found that DRD2 signaling functionally alters glucose and lipid metabolisms in glioblastoma cells, and the effect of ONC201 on oxidative phosphorylation and glycolytic activity was dependent on genetic background of tumor cells." (PMID 33557912, 2021). "Blockade of this pathway through DRD2 antagonism or gene silencing has in vitro and in vivo anti-proliferative effects in glioblastoma." (PMID 33557912, 2021). "DRD2 blockade is sufficient to inactivate growth factor signaling and induce tumor cell death in preclinical models of glioblastoma and other malignancies." (PMID 29108308, 2017). "DRD2 has emerging as a novel therapeutic target in glioblastoma and other cancers based on a series of studies that have demonstrated its selective overexpression in malignant tissues and the anticancer effects of its antagonism." (PMID 29108308, 2017). "DRD2 is a G protein-coupled receptor that is overexpressed in glioblastoma and controls growth factor signaling through cross-talk mechanisms involving beta-arrestin and scaffold proteins." (PMID 29108308, 2017). "It was recently reported that glioblastoma specimens from patients have a 4–17-fold increase in dopamine receptor D2 (DRD2) mRNA or 2–4-fold enhancement in protein expression." (PMID 26771606, 2016). "The authors subsequently demonstrated that one of these pathways, mediated by the dopamine receptor subtype 2 (DRD2), plays a critical role in glioblastoma mitogenic signaling." (PMID 24657925, 2014). "Treatment with independent si-/shRNAs against DRD2 or with DRD2 antagonists suppressed the growth of patient-derived glioblastoma lines both in vitro and in vivo." (PMID 24658464, 2014). "Our results suggest combined EGFR and DRD2 inhibition as a promising strategy for glioblastoma treatment." (PMID 24658464, 2014). "Our data suggest that FDA-approved DRD2 antagonists, such as haloperidol, warrant consideration as potential glioblastoma therapy." (PMID 24658464, 2014). "However, a growing body of literature reveals increased mRNA and protein expression of the G protein-coupled dopamine receptor D2 (DRD2) in many tumors including breast, colon, pancreas, prostate, glioblastoma, lymphoma, and endometrial cancer." (PMID 33557912, 2021). "Knockdown of DRD2 or inhibition with pharmacologic antagonists in glioblastoma, pituitary tumors, pancreatic and breast cancer cells leads to inhibition of proliferation and migration as well as anti-tumorigenic effects in number of different xenograft mouse models." (PMID 33557912, 2021). "Another report supports the tumorigenic role of DRD2 in cancer stem cells, by demonstrating that DRD2 is a downstream target of the repressor element-1 silencing transcription factor (REST) that drives tumorigenesis in glioblastoma stem-like cells by regulating invasion and apoptosis." (PMID 34422720, 2021).
glioblastoma (continued). "The same authors subsequently demonstrated that one of these pathways, mediated by the dopamine receptor subtype 2 (DRD2), plays a critical role in glioblastoma mitogenic signaling and that DRD2 antagonists, clinically used as anti-psychotic drugs, harbor anti-glioblastoma activities." (PMID 29844869, 2018). "A recent report indicated a role for the dopamine receptor D2 in glioblastoma growth." (PMID 28051998, 2017). "Importantly, the authors demonstrated that DRD2 antagonists, clinically used as anti-psychotic drugs, harbor anti-glioblastoma activities." (PMID 24657925, 2014). "However, the correlation between PD-L1 and DRD2 has not been well-investigated in context to human cancer except for one recent study where Paliperidone (a DRD2 antagonist) reduced PD-L1 expression in glioblastoma cells and increased survival in a mouse model of glioblastoma." (PMID 36072788, 2022). "Prabhu et. al. recently found a DRD2 + DRD5- biomarker signature that significantly predicts the sensitivity to ONC201 in pre-clinical models and is associated with improved outcomes in patients treated with ONC201 in a Phase II clinical trial for recurrent glioblastoma." (PMID 33557912, 2021). "In glioblastoma (GBM), tumor cells autonomously synthesize dopamine, activating dopamine receptor D2 and significantly increasing glucose uptake and glycolytic flux, establishing a unique, dopamine-driven metabolic program." (PMID 41163091, 2025). "Combined inhibition of DRD2 and Epidermal Growth Factor Receptor (EGFR) led to synergistic tumoricidal activity as well as ERK suppression in independent in vivo and in vitro glioblastoma models." (PMID 24658464, 2014). "Validating this result, DRD2 transcript and protein expression were found increased in clinical glioblastoma specimens when compared to matched non-neoplastic tissues." (PMID 30909628, 2019). "Supporting the importance of DRD2 in glioblastoma, DRD2 mRNA and protein expression were elevated in clinical glioblastoma specimens relative to matched non-neoplastic cerebrum." (PMID 24658464, 2014). "Importantly, glioblastoma lines derived from independent genetically engineered mouse models (GEMMs) were more sensitive to haloperidol, an FDA approved DRD2 antagonist, than the premalignant astrocyte lines by approximately an order of magnitude." (PMID 24658464, 2014). "Similarly, expression of DRD2 mRNA and protein was notably elevated in glioblastoma specimens relative to non-malignant cerebrum, and the pro-proliferative influence of DRD2 was mediated in part through the Ras/ERK signaling axis." (PMID 33557912, 2021).